VHLL (VHL like)
Description:
Functions as a dominant-negative VHL to serve as a protector of HIFalpha.
Synonyms: VLP; VHLP
Tractability: No criterion of Open Targets' tractability assessment is met for any kind of drug.
Gene: Protein-coding gene on chromosome 1 (156,298,624 to 156,299,307, reverse strand). Ensembl gene ENSG00000189030.
Gene Ontology:
Molecular function: protein binding
Genetic constraint (gnomAD): Loss-of-function variants: 7 observed, 7.28 expected, observed/expected ratio (o/e) 0.96, 90% interval 0.54 to 1.71. That is too few expected variants to judge how well the gene tolerates losing a copy. Missense variants: 155 observed, 184.43 expected, observed/expected ratio (o/e) 0.84, 90% interval 0.74 to 0.96. Synonymous variants: 77 observed, 79.89 expected, observed/expected ratio (o/e) 0.96, 90% interval 0.8 to 1.16.
Homologues: Orthologues: macaque VHLL (80% identical), tropical clawed frog vhl (32% identical), zebrafish vhl (32% identical), Drosophila melanogaster Vhl (17% identical). Paralogues in human: VHL (65% identical).
Diseases named in the same sentence as VHLL in open-access papers:
VHLL is named in the same sentence as 3 diseases in open-access papers, as found by Europe PMC text mining. Sharing a sentence is not in itself a finding about the gene and the disease. The quoted sentences say what the papers report.
colorectal cancer (1 paper, 2020). A primary or metastatic malignant neoplasm that affects the colon or rectum. "Owing to the successful 3D culture of colorectal cancer tissue derived organoids, we were able to test the clinical potential of β-catenin targeted degrader xStAx-VHLL ex vivo." (PMID 32550000, 2020). "More importantly, xStAx-VHLL could potently inhibit the survival of colorectal cancer patient-derived organoids." (PMID 32550000, 2020).
tumor (3 papers, 2020 to 2025). "More importantly, xStAx-VHLL was able to impede in vivo tumor formation in nude mouse xenografts and suppress the existing tumors in APCmin/+ mouse models, while xStAx had minimal effect in vivo." (PMID 32550000, 2020). "Further, in CRC patient-derived tumor organoids, xStAx-VHLL effectively restrained the survival of tumor organoids, which highlighted its clinical potential." (PMID 32550000, 2020). "xStAx-VHLL also restrained tumor formation in xenograft mouse models and reduced intestinal tumors in APCmin/+ mice." (PMID 32550000, 2020). "xStAx-VHLL also efficiently inhibited Wnt signaling as well as cell proliferation, intestinal organoid growth, and tumor formation." (PMID 32550000, 2020). "Consistently, immunoblotting analysis of the tumor extracts showed that the β-catenin protein level in the xStAx-VHLL group was apparently decreased compared with other groups, indicating that xStAx-VHLL achieved effective and durable degradation of β-catenin." (PMID 32550000, 2020). "Nonetheless, as the first-generation PROTAC β-catenin degrader, xStAx-VHLL has already showed great promise in inhibiting tumor growth in vivo, and it could be employed as the leading PROTAC for further optimization in Wnt signaling-interfering cancer therapy." (PMID 32550000, 2020). "Furthermore, xStAx-VHLL could effectively restrain tumor formation in BALB/C nude mice, and diminish the existing tumors in APCmin/+ mice." (PMID 32550000, 2020). "xStAx-VHLL effectively inhibits the Wnt signaling of cancer cells and APC−/− organoids and reduces the tumor burden in BALB/c nude mice by targeting β-catenin for efficient degradation." (PMID 40649987, 2025). "Although tumor number was slightly decreased in the SAHPA1-VHLL and xStAx groups, the xStAx-VHLL dramatically reduced tumor number compared with that of 11 weeks-old mice before treatment (day 0) or with vehicle DMSO treatment." (PMID 32550000, 2020).
cancer (2 papers, 2020 to 2025). A tumor composed of atypical neoplastic, often pleomorphic cells that invade other tissues. "We found that xStAx-VHLL manifested strong inhibition of Wnt signaling and sustained degradation of β-catenin in cancer cells and the intestinal organoids derived from wild-type and APC–/– mice." (PMID 32550000, 2020). "The obtained xStAx-VHLL sustained β-catenin degradation and manifested strong inhibition of Wnt signaling in cancer cells and in APC−/− organoids." (PMID 32550000, 2020). "We demonstrated that xStAx-VHLL acted as a potent PROTAC β-catenin degrader, efficiently promoting the proteasomal degradation of endogenous β-catenin in cancer cells and intestinal organoids." (PMID 32550000, 2020).